KPNA4 (karyopherin subunit alpha 4)
Diseases named in the same sentence as KPNA4 in open-access papers (continued):
Sharing a sentence is not in itself a finding about the gene and the disease.
tumor (continued). "Moreover, we found that the levels of circ_ZFR, KPNA4 mRNA and KPNA4 protein were reduced and the level of miR-195-5p was raised in the tumor tissues obtained from PTX + sh-circ_ZFR groups compared to PTX + sh-NC groups." (PMID 33407505, 2021). "Lastly, rescue assays affirmed the tumor-restraining role of miR-596-BRD4/KPNA4 axis in EOC." (PMID 32943995, 2020). "Hereby we postulate that KPNA4 may play a tumor-promoting role via FAK signaling." (PMID 35425701, 2022). "However, tumors with higher T stage or N stage had a tendency to express higher level of KPNA4, indicating that KPNA4 may promote tumor infiltration and lymph node metastasis." (PMID 35425701, 2022). "This study investigated the prognostic value of KPNA4 and its potential functions in PDAC and tumor microenvironment." (PMID 35425701, 2022). "There was an increasing trend in KPNA4 mRNA and protein levels from normal tissues to PTX-sensitive tumor tissues and then to PTX-resistant tumor tissues." (PMID 33407505, 2021). "In summary, these results suggest that high-expressed KPNA4 in PDAC may correlate with immunosuppressive cells infiltration and T cell exhaustion, thereby inhibiting anti-tumor immunity." (PMID 35425701, 2022). "The results further revealed that high KPNA4 expression had a significant correlation with poor survival in patients regardless of histological grades, indicating that the prognostic value of KPNA4 was independent of tumor malignancy." (PMID 35425701, 2022). "KPNA4 expression in normal liver tissue was lower than that in other normal tissues (liver/other normal: logFC = -0.80); similarly, in HCC tissue, the level was lower than other cancerous samples (HCC/all tumor: logFC = -0.40)." (PMID 33535183, 2021). "Previous studies showed that miR-567 could regulate KPNA4, ATG5 and then inhibited tumor progression or chemoresistance." (PMID 34226531, 2021). "Furthermore, miR-361 also suppressed the expression of multiple prometastatic genes and tumor microenvironment-related genes, including MEF2D, ROCK1, WNT7A, VEGF-A, PDE4B, and KPNA4." (PMID 31287002, 2019). "Therefore, considering that KPNA4 may participate in shaping the immunosuppressive TME, KPNA4-targeted strategy is expected to reverse the tumor-promoting microenvironment and enhance anti-tumor immunity." (PMID 35425701, 2022). "This study revealed that KPNA4 is an independent prognostic biomarker for PDAC and plays a tumor-promoting role by facilitating proliferation and migration of cancer cells and participating in immune infiltration, which may be mediated by FAK signaling and PD-L1 expression." (PMID 35425701, 2022). "Finally, functional analyses demonstrated that KPNA4 may be involved in focal adhesion kinase (FAK) signaling, which can promote tumor progression and metastases by acting on tumor cells and stromal cells in the tumor microenvironment." (PMID 35425701, 2022).
cancer (11 papers, 2019 to 2025). A tumor composed of atypical neoplastic, often pleomorphic cells that invade other tissues. "TIMER2.0 database further revealed that the expression of KPNA4 was also positively correlated with the infiltration of regulatory T cells (Tregs) and cancer-associated fibroblasts (CAFs)." (PMID 35425701, 2022). "Although KPNA4 showed discordant expression change in most cancer types, it was consistently upregulated in five cohorts of PDAC." (PMID 35425701, 2022). "Next, we used this database to determine the difference of KPNA4 mRNA expression in various cancers, and found that HCC is the lowest expression type among them." (PMID 33535183, 2021). "Overall, we evidenced the oncogenic role of lncRNA ST7-AS1 in LUAD, the overexpression of which promoted viability, EMT, migration and invasion of cancer cells via sponging miR-181b-5p, and subsequently releasing its suppression on KPNA4." (PMID 33327962, 2020). "Analysis of KPNA4 amplification across multiple cancers revealed that HNSCC showed remarkable amplification, which was also observed other types of SCCs arising from lung and cervix (data not shown)." (PMID 31822798, 2020). "CXXC4 levels, along with KPNA4 and SMC4, have been associated with cancer progression." (PMID 34187551, 2021). "Concomitantly, miR-181b-5p was significantly up-regulated, while KPNA4 reduced on both mRNA and protein levels in sh-ST7-AS1 xenografts, supporting the association between the anti-cancer activity of sh-ST7-AS1 and the up-regulation of miR-181b-5p as well as the down-regulation of KPNA4." (PMID 33327962, 2020). "Here, consistent with previous reports, we demonstrated that ST7-AS1 promoted multiple malignant phenotypes of LUAD cells by sponging miR-181b-5p, and thus up-regulating KPNA4, which also indicated that KPNA4 could be a potential target for cancer therapy." (PMID 33327962, 2020). "Notably, KPNA4 mRNA levels were especially higher in HNSCC based on Cancer Cell Line Encyclopedia datasets." (PMID 31822798, 2020). "However, the prognostic value of KPNA4 in other cancers has yet to be reported." (PMID 35425701, 2022). "Therefore, KPNA4 may mediate the infiltration of these immunosuppressive immune cells, thereby promoting cancer progression." (PMID 35425701, 2022). "Next, we investigated whether KPNA4 is functionally involved in cancer cell biology." (PMID 31822798, 2020). "Next, we compared the KPNA4 transcript amounts between 433 cases of HNSCC patients with various pathological stages and 43 cases of normal subjects via Cancer RNA-Seq Nexus (See “URLs”)." (PMID 31822798, 2020). "We also discovered 22 riboSNitch-depleted 3′UTRs, but only two of them (KPNA4 and GABBR2) were identified as cancer-specific." (PMID 31160636, 2019). "However, whether KPNA4 relates to immune infiltration in other cancers has not been elucidated yet." (PMID 35425701, 2022).
infection (8 papers, 2013 to 2026). The state of being infected such as from the introduction of a foreign agent such as serum, vaccine, antigenic substance or organism. "Interestingly we detected another family of nuclear transporter KPNA1, KPNA2, and KPNA4 to be significantly decreased at the later time point of infection." (PMID 34006825, 2021). "Binding of 4b to KPNA4 during infection inhibited its interaction with NF-κB-p65 subunit." (PMID 29370303, 2018). "Interestingly, 4b binding to KPNA4 during infection inhibited its interaction with NF-κB-p65 subunit." (PMID 29370303, 2018). "In enterovirus (EMCV) infection, DDX56 directly binds KPNA3/KPNA4, which are critical nuclear import receptors." (PMID 41217109, 2025). "In the context of infection, MERS-CoV 4b protein also preferentially bound to KPNA4 over all other karyopherins, including KPNA3." (PMID 29370303, 2018). "Additionally, ferret infection with SARS-CoV-2 showed an increase in KPNA1, KPNA4, and KPNA5 expression (p = 0.0473, p = 0.0449, and p = 0.0371, respectively) when compared with the mock treatment." (PMID 34696514, 2021). "In addition, the expression levels of KPNB1, KPNA1, KPNA2, KPNA4, KPNA6, and KPNA7 changed with the infection time of the three strains while KPNA3 and KPNA5 did not change with the incubation time." (PMID 40687856, 2025).
neurodegenerative disease (2 papers, 2022 to 2025). A disorder of the central nervous system characterized by gradual and progressive loss of neural tissue and neurologic function. "Abundant KPNA3 and KPNA4 isoforms play important roles in neuronal cell physiology and their dysregulation was linked to neurodegenerative diseases." (PMID 35927988, 2022). "As KPNA4 dysfunction has in various studies been implicated in the pathophysiology of ALS, a neurodegenerative disease affecting the upper and the lower motoneuron, we assessed the neuromuscular function in KPNA4-deficient mice over their lifespan in both sexes." (PMID 40565582, 2025). "KPNA3 and KPNA4 were also studied regarding the transport of TAR DNA-binding protein 43 (TDP-43) and the formation of aggregates of this protein in the central nervous system, which is a hallmark of many neurodegenerative diseases." (PMID 35927988, 2022).
KPNA4 also shares sentences with these, for which no sentence is quoted: epithelial ovarian cancer (2 papers); osteosarcoma (2); viral infection (2); Anxiety (1); atherosclerosis (1); attention deficit-hyperactivity disorder (1); chronic pancreatitis (1); colorectal cancer (1); COVID-19 (1); diabetes mellitus (1); esophageal carcinoma (1); gastric cancer (1); lung squamous cell carcinoma (1); melanoma (1); non-small cell lung carcinoma (1); ovarian cancer (1); pancreatic ductal adenocarcinoma (1); prostate tumor (1); renal cell carcinoma (1); squamous cell carcinoma (1).